DAXX (death domain associated protein)
Diseases named in the same sentence as DAXX in open-access papers (continued):
Sharing a sentence is not in itself a finding about the gene and the disease.
cancer (continued). "By binding with SUMOylated-SMAD4, DAXX inhibits the tumor suppressive effect of transforming growth factor-β (TGF-β) signaling mediated by SMAD4, which affects the growth arrest and apoptosis of cancer cells." (PMID 36911524, 2023). "Loss of ATRX and DAXX is strongly related to alternative lengthening of telomeres (ALT), a process characteristic of cancer cells in which telomere length is retained through a non-telomerase-dependent mechanism." (PMID 32533344, 2020). "In a few clinical studies, DAXX or DAXX/ATRX expression loss was correlated with chromosomal instability and predicted relapse in patients with low-stage cancer (i.e., stage I–III with no distant metastasis) with DNA hypomethylation regulation." (PMID 31614769, 2019). "Indeed, in vitro switch of TA to ALT activity in telomerase-positive cancer cells was successfully demonstrated by inducing telomere-specific DNA damage, ATRX and DAXX knockdown, and deletion of hTERT." (PMID 28513547, 2017). "Mutations of DAXX, ATRX and H3.3 have also been found to be associated with telomerase-negative human cancer cells that undergo ALT." (PMID 24563217, 2014). "We showed that overexpression of TPP1ΔOBRD, ATRX knockdown, DAXX deletion and TERT KO in telomerase-positive HTC75 cancer cells could promote ALT phenotypes by increasing APBs and C-circles, elongating telomeres and producing heterogeneous telomeres, which were very similar to ALT cells." (PMID 27578458, 2016).
infection (18 papers, 2009 to 2025). The state of being infected such as from the introduction of a foreign agent such as serum, vaccine, antigenic substance or organism. "The inclusion of the H3 subunit variant, H3.3, is of particular interest in the context of infection due to its binding to the histone chaperone, death domain-associated protein (Daxx) (80, -, 82)." (PMID 37439556, 2023). "The same study also observed that DEK, a H3.3 chaperone that regulates H3.3 distribution to HIRA and ATRX/DAXX, associated with the viral genome for most of the first 6 h of infection." (PMID 33909709, 2021). "Relevant for infection and inflammation, we observed upregulation of DAXX, involved in transcription repression and apoptosis, and ANG, involved in angiogenesis." (PMID 41416938, 2025). "DAXX fulfills all of the criteria defining a bona fide SARS-CoV-2 restriction factor: knocking-out endogenous DAXX leads to enhanced viral replication, while over-expression of DAXX restricts infection." (PMID 35508460, 2022). "Within hours of infection, DAXX re-localizes to sites of viral replication in the cytoplasm, targeting an early, post-entry step of the viral life cycle such as viral transcription or uncoating." (PMID 35508460, 2022). "Here, using the in1374-based in cellula model of infection, we showed that vDCP NBs contained not only the DAXX and ATRX proteins but also all the components of the HIRA complex and H3.3 itself." (PMID 30235352, 2018). "Furthermore, we found that many of IFIX interactions were lost following infection, including PML and its associated proteins (DAXX, ATRX, HIRA, etc.)." (PMID 25665578, 2015). "Then, as viral replication and innate immune signaling proceed during infection with ICP0 RF, by 8 hpi, the interaction profile of SLFN5 remains correlated with IFI16, while those of PML, DAXX, and SP100 diverge to cluster with one another." (PMID 40577456, 2025). "Thus, it is apparent that ATRX and DAXX have distinct roles in early transcriptional regulation and that ATRX promotes transcription upon initial infection." (PMID 41012597, 2025). "At 24 h post-infection however, DAXX was completely absent from nuclear bodies, and was found almost exclusively in the cytoplasm, in close association with dsRNAs, likely representing SARS-CoV-2 replication sites." (PMID 35508460, 2022). "DAXX protein and mRNA levels were slightly elevated in SLK cells only, but importantly no loss of DAXX was detected in either cell line upon infection." (PMID 33479235, 2021). "DAXX depletion has consistently resulted in comparatively smaller increases in viral yield than ATRX depletion, and DAXX has recently been reported to have potential roles in viral activities during late infection." (PMID 33909709, 2021). "It is possible that DAXX is restrictive while in complex with ATRX but at a later stage of infection, after dispersion of PML-NBs and degradation of ATRX, DAXX may promote HSV gene expression or replication." (PMID 30465651, 2018). "In contrast, viruses like KSHV, for which the default outcome of infection in most if not all cells is latency, encode for vFGARATs that are not capable of degrading PML but affect other components of ND10-NBs like SP100, DAXX or ATRX, and often in a more subtle way than plain degradation." (PMID 29065450, 2017).
digestive tumors (1 paper, 2022). "In conclusion, current research on DAXX in digestive tumors has focused on DAXX transcriptional regulation." (PMID 36428674, 2022).
epithelial neoplasm (1 paper, 2025). A benign or malignant neoplasm that arises from and is composed of epithelial cells.
DAXX also shares sentences with these, for which no sentence is quoted: mental retardation (7 papers); colon NEC (3); soft tissue sarcoma (3); clear cell renal cell carcinoma (2); intellectual disability syndrome X-linked (2); leukemia (2); multiple endocrine neoplasia type 1 (2); pancreatic NEN (2); acinar cell carcinoma (1); alpha thalassemia/mental retardation syndrome X-linked (1); Alzheimer disease (1); anaplastic thyroid carcinoma (1); benign tumors (1); bipolar disorder (1); cervical tumor (1); chronic myelogenous leukemia (1); cutaneous melanoma (1); Dengue hemorrhagic fever (1); diabetes (1); ductal adenocarcinoma (1); ductal carcinomas (1); esophageal cancer (1); gastrointestinal neuroendocrine tumors (1); gastrointestinal stromal tumor (1); hepatic angiosarcomas (1); hepatocellular carcinoma (1); herpesvirus infection (1); Insulin resistance (1); large cell neuroendocrine carcinoma (1); liposarcoma (1).
A further 24 diseases each share a sentence with DAXX in 1 paper.